ACSS2 (acyl-CoA synthetase short chain family member 2)
Diseases named in the same sentence as ACSS2 in open-access papers (continued):
Sharing a sentence is not in itself a finding about the gene and the disease.
tumor (continued). "ACSS2 expression is up-regulated under metabolically stressed conditions (low oxygen and low nutrient/lipid availability) and ACSS2 silencing has been shown to reduce the growth of tumor xenografts." (PMID 34203535, 2021). "The impact of inhibited expression of FASN, ACSS2, and SREBP1c in MJ-exposed tumor cells was also investigated by assessing tumor cell membrane’s stability through examining the osmotic fragility." (PMID 33718176, 2021). "Clearly, ACSS2 can have contradictory actions in different tumor types, further highlighting the fact that its actions in oncogenesis and tumor progression involve more than lipid synthesis." (PMID 33304273, 2020). "Intriguingly, adult ACSS2 knockout mice appear phenotypically normal, however, they exhibit reduced tumor burdens in models of hepatic cancer." (PMID 33304273, 2020). "In fact, they demonstrated the crucial role of ACSS2 for cellular and tumour growth under stress conditions by using knock‐down or knockout experiments." (PMID 33107196, 2020). "Our previous work demonstrated that KHK-A and ACSS2 are two key metabolic enzymes that have important roles in tumor development." (PMID 31750240, 2019). "The metabolism-reprogramming marker ketohexokinase (KHK)-A and acetyl-CoA synthetase 2 (ACSS2) phosphorylation at S659 (ACSS2 pS659) play important roles in tumorigenesis and tumor development." (PMID 31750240, 2019). "Collectively, these results suggest that ACSS2 pS659 plays an important role in tumor metabolism reprogramming through its nuclear function." (PMID 31750240, 2019). "To determine the relationship of ACSS2 to lipid metabolism and cisplatin resistance at the molecular level, we performed immunohistochemical (IHC) staining of tumor microarrays using a commercially available ACSS2 antibody." (PMID 29568353, 2018). "This suggests that, by recycling acetyl-CoA, nuclear ACSS2 is critical for cell survival and tumor growth under nutrient restriction." (PMID 29991493, 2018). "Although ACSS2 can positively or negatively impact tumour progression, depending on the tumour type, its production of acetyl-CoA is required for the growth and progression of liver cancer in murine models." (PMID 29739810, 2018). "Our IHC analysis further confirmed that ACSS2 is more abundantly expressed in tumor samples of higher grades." (PMID 29568353, 2018). "It was also concluded that ACSS2 and p-(Ser473)-Akt/Rictor expression differences showed high score variability among tumours; IHC staining intensities were scored between 1+ and 3+ in same grade IDH-mutant and wild-type tissues." (PMID 30574020, 2018). "The nuclear-cytosolic acetyl-CoA synthetase 2 (ACSS2) was found to sustain the growth of hypoxic tumor cells." (PMID 28099844, 2017). "This would lead to higher fractional acetate labeling in high ACSS2 tumors than in low ACSS2 tumors because, in the latter, tumor cells release more unlabeled acetate." (PMID 28099844, 2017). "Acetyl-CoA synthetase 2 (ACSS2) generates acetyl-CoA from acetate and is important for tumor growth." (PMID 28099844, 2017). "In contrast, mice with flank tumors derived from Acss2 shRNA knockdown or CYT Acss2 knockdown/rescue cells have blunted primary tumor weight and luciferase activity as well as metastatic lung tumor activity." (PMID 29281714, 2017). "The cytosol-restricted Acss2 examined in this study retains lipid synthesis capacity, yet is markedly impaired in tumor cell function, indicating Acss2 possesses other properties that regulate tumor growth and metastasis." (PMID 29281714, 2017). "Acetate also stimulates flank tumor growth and metastasis in mice in an ACSS2 and HIF-2 dependent manner." (PMID 25689462, 2015). "To investigate the functional interplay between ACSS2 and autophagy in tumor cell behavior, we systematically modulated autophagic activity in shACSS2 cells using pharmacological agents: chloroquine as an autophagy inhibitor and Torin 1 as an autophagy inducer." (PMID 40858538, 2025).
tumor (continued). "Furthermore, the results of HE staining indicated that compared with the tumor tissues in the ACSS2 knockdown group, the tumor tissues in the NC group exhibited higher cellular atypia." (PMID 40858538, 2025). "This further substantiates the notion that ACSS2 knockdown can impede tumor growth." (PMID 40858538, 2025). "HNSCC tumor tissues and cell lines were analyzed for ACSS2 protein expression." (PMID 40858538, 2025). "Thus, combination therapy with ACSS2 inhibitors can effectively inhibit acetate‐dependent tumor development and increase the antitumor efficacy of ACLY inhibitors." (PMID 41346571, 2025). "One study showed that adult mice with Acss2 deficiency exhibit a significant reduction in tumor burden in hepatocellular carcinoma without deficits in growth or development." (PMID 40814339, 2025). "It was hypothesized that the abnormally increased ACSS2 in the tumor tissues of patients with PNETs may have led to the accumulation of local acetyl‐CoA and increased histone acetylation modification." (PMID 40791180, 2025). "The results suggested that apoptosis of CD8+ T cells originally co‐expressing Fas might have occurred due to the continuous expression of ACSS2 and FasL in tumor cells." (PMID 40791180, 2025). "However, ACSS2 inhibition significantly inhibited tumor growth, and the addition of trametinib to ACSS2 inhibition further arrested tumor progression." (PMID 40131933, 2025). "Notably, the ACSS family (notably ACSS2) can synthesize acetyl‐CoA via acetate metabolic bypass, which induces drug resistance in tumor cells to ACLY inhibitors." (PMID 41346571, 2025). "Collectively, the present study revealed the posttranslational control of ACSS2 in PNETs via the acetylation and its mechanism of inducing apoptosis of T cells in the microenvironment of PNETs via the Fas/FasL pathway and then promoting tumor immune escape." (PMID 40791180, 2025). "ACSS2 is known to be important for tumor metabolism in hypoxic environments." (PMID 38851813, 2024). "Using isotopic labeling methods, researchers have found that under low-oxygen or low-serum conditions, tumor cells control acetate uptake through ACSS2 and utilize acetate to synthesize acetyl-CoA to promote fatty acid synthesis, thereby sustaining the survival of tumor cells." (PMID 38535331, 2024). "In contrast, ACSS2 knockdown inversely impacts tumor proliferation." (PMID 38887280, 2024). "Notably, hypoxia and glucose deprivation have been shown to stimulate ACSS2 signaling in the tumor microenvironment." (PMID 38515158, 2024). "Hypoxia in the tumor micro‐environment leads to up‐regulation of lipid metabolism‐related genes, such as ACSS2, which enhances lipid metabolism reprogramming through pathways like HMGCS1 mediated PI3K/AKT/mTOR, promoting the progression of various cancers, including pNETs." (PMID 39524139, 2024). "However, they ACSS2 inhibition significantly inhibited tumor growth, and addition of trametinib to ACSS2 inhibition further arrested tumor progression." (PMID 38464238, 2024). "Thus, these novel ACSS2 inhibitors block tumor growth and survival in the brain microenvironment while causing no overt toxicity to normal brain tissue." (PMID 38818373, 2024). "Moreover, tumour cells can take up acetate and convert it to acetyl‐CoA through ACSS2, resulting in elevated c‐Myc acetylation, which in turn reprograms tumour metabolism and enhances PD‐L1 expression and immune evasion." (PMID 39568157, 2024). "Hence, ACSS2 is essential for tumor growth under metabolic stress, and its expression can predict tumor staging and patient prognosis." (PMID 39834807, 2024). "ACSS2 is required for tumor growth of KRASG12V mouse colon epithelial cells." (PMID 38464238, 2024). "HIF-2 selective or co-regulated target genes associated with tumor growth and metastasis (VEGFa, PAI1, MMP9, GLUT1) were induced in acetylation-intact (K3) HIF-2α and nuclear-localizable (WT) Acss2 knockdown/rescue cells under hypoxia and low glucose conditions." (PMID 36862715, 2023).
tumor (continued). "In addition, under metabolic stress such as hypoxia or low serum, ACSS2 is required for the utilization and uptake of acetate and also supports the biosynthesis of membrane phospholipids for tumor cell growth." (PMID 38060103, 2023). "In mice, injection of ACSS2 shRNA in GB cells significantly inhibits tumor growth." (PMID 37298093, 2023). "In addition to mediating the epigenetic regulation of gene transcription by histone acetylation, another important function of the ACSS family, including ACSS2, in tumor biology is to mediate fatty acid synthesis for tumor growth." (PMID 36707625, 2023). "Whether PDE remain masked in wildtype Acss2 expressed in solid tumors, or whether they are unmasked in some regions of solid tumors due to local effects of the tumor microenvironment, remains to be determined." (PMID 36862715, 2023). "Therefore, it is clear that ACSS2 supports the development of tumor cells by mediating macropinocytosis and muscle wasting." (PMID 37720505, 2023). "Similarly, related studies in the gastrointestinal tract showed that reduced ACSS2 expression promoted tumor growth." (PMID 35740562, 2022). "In addition, studies in tumors have shown that cancer cells adapt to the growth conditions in the tumor microenvironment (TME) by activating or increasing the expression level of ACSS2 under metabolic stress." (PMID 35798917, 2022). "However, some studies have indicated that the decrease of ACSS2 can promote tumor progression, and promoting the expression of ACSS2 can inhibit tumor growth and development." (PMID 36119478, 2022). "In mouse experiments, hyperphosphorylation of ACSS2 at S267 was found to promote tumor growth." (PMID 35798917, 2022). "However, there are inhibitors of ACSS2 combined with immunotherapy and radiotherapy to reduce tumor drug resistance and radiotherapy resistance, which is expected to be further studied." (PMID 35740562, 2022). "The increase in phosphorylation of ACSS2 at S659 also promoted tumor growth." (PMID 35798917, 2022). "It is well known that ACSS2 has tumor specificity, and the opposite results of ACSS2-mediated autophagy in different tumors may be due to the complexity of autophagy, or the tumor specificity of ACSS2." (PMID 35740562, 2022). "Interestingly, recent evidence from in vitro studies on various tumor cell lines has shown that ACSS2 also catalyzes a reverse reaction converting acetyl-CoA to acetate in cancer cells." (PMID 35798917, 2022). "ACSS2 is closely related to hypoxia due to the biological characteristics of tumor growth." (PMID 35798917, 2022). "ACSS2 generates acetyl-CoA both in the cytosol and in the nucleus for bioenergetic processes and histone acetylation, thereby influencing the metabolism and gene expression of the tumor cells." (PMID 36142502, 2022). "The expression of GRAMD1C, NFKBIA, and ACSS2 was significantly higher in normal tissues than in tumour tissues (P < 0.001, P = 0.0096, and P < 0.001, respectively), which indicated that CD24 and INHBA were risk genes and that GRAMD1C, NFKBIA, and ACSS2 were protective genes." (PMID 35999846, 2022). "However, the completely opposite effect in the same tumor raises the suspicion that ACSS2 has different isoforms and performs different functions in different cell lines of the same tumor." (PMID 35740562, 2022). "In addition, some studies have found that ACSS2 can also promote tumor progression by affecting other immune cells and cytokines." (PMID 35740562, 2022). "In addition, under stress, the molecular signaling pathways in tumor cells undergo corresponding compensatory changes, and the compensatory increase in ACSS2 can maintain the survival of tumor cells." (PMID 35798917, 2022). "In cervical cancer, ACSS2 has also been shown to be associated with various immune cell infiltrates, especially with tumor-associated macrophages (TAM), which were not present in normal cervical tissue." (PMID 35740562, 2022).
tumor (continued). "Therefore, the tumor uptake of radioactive acetate can be used to observe the expression of ACSS2 in the cytoplasm and the lipid or lipid-soluble substances derived from acetate." (PMID 35740562, 2022). "However, in a study of esophageal squamous cancer cells, ACSS2 expression was promoted in tumor cells, although these cells were less responsive to nutrient deprivation than were normal cells." (PMID 35798917, 2022). "In addition, ACSS2 is tumor-specific, and its effect on tumors varies according to different tumor cell lines." (PMID 35740562, 2022). "ACSS2 can also cooperate with Tregs to promote tumor metastasis and invasion." (PMID 35740562, 2022). "Therefore, modulating the OGT/CDK5/ACSS2 axis constitutes a new strategy for tumor-targeted therapy." (PMID 35798917, 2022). "On the other hand, ACSS2 plays an important role for cell survival in many tumor cells." (PMID 35740562, 2022). "Similarly, in glucose-deprived or hypoxic tumor cells, the intracellular acetate level and the nuclear translocation of ACSS2 from the cytoplasm are increased." (PMID 35798917, 2022). "We evaluated the relationship between ACSS2 and diverse tumor-infiltrating immune cells." (PMID 34206705, 2021). "We found that the expression level of ACSS2 was significantly higher in CESC patients than in normal cells, and confirmed a positive correlation between the level of immune infiltration and ACSS2, thus ACSS2 as a key enzyme of tumor energy metabolism has become a new focus for researchers." (PMID 34206705, 2021). "The results from the TIMER database suggested that ACSS2 was remarkably correlated not only with tumor purity but also with the infiltrating levels of different immune cells, including CD4+ T cells, CD8+ T cells, B cells, neutrophils, macrophages, and dendritic cells, in CESC." (PMID 34206705, 2021). "We observed the gene expression levels of ACSS2 master regulators in each tumor." (PMID 34206705, 2021). "In addition to their role as alternative PET tracers for tumor imaging, they can be used to point to more sensitive tumors to the inhibition of glutamine metabolism and ACSS2, respectively." (PMID 34203535, 2021). "Recently it has been shown that ACSS2 gene expression increased under hypoxia in tumour cells; thus, the increase of this gene expression that we found in hASCs grown in the scaffold could be consequence of a limited oxygenation of the scaffold." (PMID 32932658, 2020). "In this study, we showed that the expression levels of metabolism reprogramming marker KHK-A and ACSS2 pS659 were significantly higher in NSCLC tissues than those in adjacent non-tumor tissues, and KHK-A expression levels were higher in LUAD than those in LUSC." (PMID 31750240, 2019). "Prevention of nuclear localization by a directed mutation in a putative nuclear localization signal in Acss2 abrogates HIF-2 acetylation and blunts HIF-2 dependent signaling as well as flank tumor growth for knockdown/rescue cancer cells expressing ectopic Acss2." (PMID 31725783, 2019). "These experimental results suggest that ACSS2 expression is significantly increased in BC cells and may also positively correlate with tumor grade." (PMID 29568353, 2018). "Specifically, depletion of autophagy related 5 (ATG5) or autophagy related 7 (ATG7) (loss of autophagy), or acyl-CoA synthetase short chain family member 2 (ACSS2) (acetate recapture loss) is well tolerated by most cells in culture, but can dramatically decrease tumor growth in vivo." (PMID 30104199, 2018). "Importantly, acetate supplementation promotes tumor growth and metastasis in an ACSS2- and HIF-2α-dependent manner." (PMID 29991493, 2018). "Furthermore, ACSS2 deletion diminished tumor burden in a genetically engineered mouse model of hepatocellular carcinoma." (PMID 28099844, 2017). "Only CYT Acss2 is impaired in its ability to rescue tumor cell processes." (PMID 29281714, 2017). "Oral acetate substantially affects flank tumor outcomes in an Acss2 and HIF-2 dependent manner." (PMID 29281714, 2017).
tumor (continued). "ACSS2, in essence, “recycles” two-carbon units when nutrient availability is low, which is especially relevant in the poorly perfused, hypoxic areas of the tumor." (PMID 28099844, 2017). "We find that the primary function of nuclear ACSS2 is to retain endogenous acetate released by deacetylases to maintain histone acetylation and propose that this is especially relevant in hypoxic and nutrient-limited areas of the tumor." (PMID 28099844, 2017). "Indeed, Acss2 knockdown substantially reduces acetate-derived lipid synthesis as well as flank tumor growth, consistent with previous observations implicating Acss2 in this process." (PMID 29281714, 2017). "show that, in hypoxic tumor regions, ACSS2 is prominently expressed in the nuclei of tumor cells." (PMID 28099844, 2017). "Thus, cancer cell line spheroids contain several of the conditions encountered in the tumor microenvironment that impart sensitivity to ACSS2 silencing." (PMID 28060271, 2016). "Ablation of ACSS2 impacted the growth of breast and prostate cancer xenografts suggesting that nutrient gradients do not exist in isolation within the tumor microenvironment and that cells that reside in these regions are essential for tumor progression." (PMID 28060271, 2016). "We asked if reducing ACSS2 or HIF levels affects tumor cell proliferation." (PMID 25689462, 2015). "We asked if reducing ACSS2 or HIF levels affects other tumor cell properties." (PMID 25689462, 2015). "In conclusion, these findings suggest that ACSS2 may promote the activation of the Fas/sFasL system through the expression of sFasL, which further leads to apoptosis of T cells with high FasL expression locally in the tumor." (PMID 40791180, 2025). "Consequently, focusing on ACSS2 may offer cutting-edge methods for treating tumours and ACSS2 inhibitors can be effective in halting cancer growth and can be combined with other antineoplastic drugs to reduce drug resistance." (PMID 40287570, 2025). "Finally, and most remarkably, we show that G12V mutants without ACSS2 are unable to form tumors in mice, whereas G12D mutants were still able to form and growth tumors despite ACSS2 KO, while ACSS2 inhibition in vivo results in a significant reduction in tumor growth combined with MEK inhibition." (PMID 38464238, 2024). "Similarly, ACSS2 knockdown in tumour cells abrogated the stellate cell-induced increase in tumour burden and tumour cell proliferation rates, without impacting apoptosis, in athymic (AT) nude mice orthotopically co-implanted with S2-013/CFPAC-1 tumour cells and HPS cells." (PMID 38429478, 2024). "Additionally, ACSS2 plays a crucial role in tumor metastasis and prognostic assessments." (PMID 38887280, 2024). "Next, we investigated whether ACSS2 localizes to the low-pH regions of tumours." (PMID 38429478, 2024). "Furthermore, ACSS2 knockout in two hepatocellular carcinoma models lessens the tumor burden." (PMID 36597205, 2023). "Both in vitro and in vivo experiments in mice have demonstrated that VY-3-135 could inhibit tumor growth, and VY-3-135 tested in human breast models yielded similar results, namely, tumors with a high ACSS2 expression were more sensitive to treatment and significantly inhibited tumor growth." (PMID 35740562, 2022). "In addition, ACSS2 inhibitors were found to reduce tumor resistance to cisplatin." (PMID 35740562, 2022). "Furthermore, knockdown of either ACSS1 or ACSS2 significantly reduced tumor growth in mice." (PMID 35798917, 2022). "Targeting ACSS2 may provide novel approaches for tumor treatment." (PMID 35740562, 2022). "Similarly, MJ-exposed tumor cells displayed inhibited expression of ACSS2, and SREBP1c." (PMID 33718176, 2021). "Additionally, it points to an important role for ACSS2 in the nuclei of hypoxic tumor cells." (PMID 28099844, 2017).